BYSL (bystin like)
Description:
Required for processing of 20S pre-rRNA precursor and biogenesis of 40S ribosomal subunits. May be required for trophinin-dependent regulation of cell adhesion during implantation of human embryos.
Synonyms: ENP1; BYSTIN
Tractability: Small molecule: a structure with a bound ligand is known. PROTAC: ubiquitination databases record sites on it; its protein half-life has been measured.
Gene: Protein-coding gene on chromosome 6 (41,921,229 to 41,933,050, forward strand). Ensembl gene ENSG00000112578.
Subcellular location: Cytoplasm; Nucleus, nucleolus
Subcellular location (Human Protein Atlas): Mitotic chromosome; Nucleoli; Nucleoli rim; Nucleoplasm
Pathways (Reactome):
Metabolism of RNA: Major pathway of rRNA processing in the nucleolus and cytosol
Gene Ontology:
Molecular function: protein binding; RNA binding; snoRNA binding
Biological process: regulation of protein localization to nucleolus; ribosome biogenesis
Cellular component: chromosome; membrane; nucleolus; nucleoplasm; cytoplasm; cytosol; preribosome, small subunit precursor; apical part of cell
Genetic constraint (gnomAD): Loss-of-function variants: 21 observed, 47.87 expected, observed/expected ratio (o/e) 0.44, 90% interval 0.31 to 0.63. The upper end of that interval is the gene's LOEUF score, 0.63, which puts it in group 2 of 6, group 1 being the genes least tolerant of losing a copy. Missense variants: 522 observed, 610.41 expected, observed/expected ratio (o/e) 0.86, 90% interval 0.8 to 0.92. Synonymous variants: 215 observed, 243.69 expected, observed/expected ratio (o/e) 0.88, 90% interval 0.79 to 0.99.
Homologues: Orthologues: chimpanzee BYSL (99% identical), macaque BYSL (97% identical), dog BYSL (93% identical), guinea pig BYSL (93% identical), rat Bysl (91% identical), mouse Bysl (91% identical), pig BYSL (90% identical), tropical clawed frog bysl (73% identical), zebrafish bysl (73% identical), Drosophila melanogaster bys (50% identical), Caenorhabditis elegans byn-1 (49% identical).
Diseases named in the same sentence as BYSL in open-access papers:
BYSL is named in the same sentence as 25 diseases in open-access papers, as found by Europe PMC text mining. Sharing a sentence is not in itself a finding about the gene and the disease. The quoted sentences say what the papers report.
glioma (6 papers, 2020 to 2022). A benign or malignant brain and spinal cord tumor that arises from glial cells (astrocytes, oligodendrocytes, ependymal cells). "Our data showed that silencing BYSL caused cell cycle arrest at G1 phase in glioma cells, which was further verified by the downregulation of cyclin D1 and CDKs (CDK4 and CDK6) and the upregulation of CDKIs (P21 and P27)." (PMID 33628587, 2021). "More importantly, high levels of BYSL mRNA were associated with poor prognoses, as observed in the glioma datasets from both TCGA and CGGA." (PMID 33628587, 2021). "In this study, we first investigated changes in the expression of BYSL in glioma tissues and analyzed the association of BYSL levels with patient overall survival using public datasets and our cohort." (PMID 33628587, 2021). "BYSL also reportedly promotes glioma/glioblastoma growth via the GSK-3β/β-catenin and AKT/mTOR pathways." (PMID 35508466, 2022). "BYSL expression in glioma tissues was measured by quantitative real-time PCR, Western blot, and immunohistochemistry." (PMID 33628587, 2021). "These clinical findings suggested the potential involvement of BYSL in the progression of human gliomas." (PMID 33628587, 2021). "The expression and activity of the AKT/mTOR signaling molecules were determined by Western blot analysis, and the role of BYSL in glioma growth was confirmed in an orthotopic xenograft model." (PMID 33628587, 2021). "The downregulation of BYSL inhibited proliferation, impeded cell cycle progression, and induced apoptosis in glioma cells, while the overexpression of BYSL led to the opposite effects." (PMID 33628587, 2021). "Here, we showed a significant increase in BYSL expression in various grades of glioma tissues, especially in high grade gliomas, by analyzing public datasets and our cohorts." (PMID 33628587, 2021). "In the present study, we demonstrated that BYSL mRNA and protein levels were upregulated in glioma tissues, especially in high grade gliomas." (PMID 33628587, 2021). "Silencing BYSL inhibited glioma cell proliferation, impeded cell cycle progression, and induced apoptosis, whereas overexpressing BYSL protein led to the opposite effects." (PMID 33628587, 2021). "We then identified the role of BYSL in glioma cell proliferation and apoptosis using small interfering RNA (siRNA) or lentivirus-mediated overexpression of BYSL." (PMID 33628587, 2021). "Studies have shown that BYSL contributes to tumor cell growth and survival by forming a complex with mTORC2 in gliomas." (PMID 35154253, 2021). "Different concentrations of siRNAs were used to transfect glioma cells, and qRT-PCR assays showed that 20 nM, 50 nM, and 100 nM siRNA significantly reduced the BYSL mRNA levels in U251 (all, P < 0.001) and U87 (all, P < 0.001) cells." (PMID 33628587, 2021). "The current study aimed to identify the molecular mechanism by which BYSL promoted glioma cell growth." (PMID 33628587, 2021). "To elucidate the molecular mechanism by which BYSL promoted glioma cell growth and survival, we analyzed the STRING and IntAct databases." (PMID 33628587, 2021). "We established stable glioma cell lines overexpressing BYSL by lentivirus infection of U87 and U251 cells." (PMID 33628587, 2021). "In addition, higher BYSL levels were associated with shorter survival times in the TCGA (n = 674, P = 0.018) and CGGA (n = 401, P = 0.31) glioma datasets." (PMID 33628587, 2021). "To determine whether the BYSL mRNA expression profiles reflected protein levels, we next measured the BYSL protein in various grades of glioma tissues." (PMID 33628587, 2021). "We aimed to determine the role and mechanism of BYSL in glioma cell growth and survival." (PMID 33628587, 2021). "In addition, knockdown of BYSL significantly decreased the cell viability in primary glioma cells at 24 h (GBM-01: P = 0.002; GBM-03: P < 0.001), 48 h (GBM-01: P = 0.011; GBM-03: P = 0.005), and 72 h (GBM-01: P < 0.001; GBM-03: P = 0.004)." (PMID 33628587, 2021).
glioma (continued). "Indeed, the overexpression of BYSL caused a significant increase in the protein levels of RIOK2, AKT, PARS40, mTOR, P70S6K, and S6 in glioma cells." (PMID 33628587, 2021). "High expression of BYSL in glioma tissues promoted tumor cell growth and survival." (PMID 33628587, 2021). "In addition, experiments with a glioma orthotopic xenograft model showed that silencing BYSL or RIOK2 decreased the growth of tumors and prolonged the survival times of tumor-bearing mice." (PMID 33628587, 2021). "The BYSL mRNA and protein levels were elevated in glioma tissues." (PMID 33628587, 2021). "In addition, BYSL is co-expressed with RIOK2 in glioma cells and is positively correlated with RIOK2 at both the gene and protein levels in glioma tissues." (PMID 33628587, 2021). "Then, we confirmed the promotion of EMT by BYSL in glioma stem cells (GSCs)." (PMID 33178594, 2020). "In addition, the role of BYSL in promoting EMT was further confirmed in a glioma stem cell line derived from a GBM patient." (PMID 33178594, 2020). "Therefore, BYSL may be a useful biomarker for astrocyte proliferation, but it cannot distinguish between glioma and gliosis." (PMID 33628587, 2021). "Therefore, knockdown of BYSL may impair pre-rRNA processing and nucleolar assembly, thereby impeding mitotic progression and proliferation in glioma cells." (PMID 33628587, 2021). "Mechanistically, BYSL activated the AKT pathway by regulating RIOK2 and mTOR, acting as an oncogene in gliomas." (PMID 35473611, 2022). "Because BYSL, RIOK2, and mTOR existed in the same complex, we next identified the role of BYSL in regulating RIOK2, AKT, and mTOR signaling in glioma cells." (PMID 33628587, 2021). "We identified a complex consisting of BYSL, RIOK2, and mTOR, and observed co-localization and positive correlations between BYSL and RIOK2 in glioma cells and tissues." (PMID 33628587, 2021). "Thus, we hypothesized that BYSL may contribute to human glioma growth." (PMID 33628587, 2021). "In addition, endogenous mTOR co-immunoprecipitated with RIOK2 and BYSL in BYSL-overexpressing cells and endogenous BYSL co-immunoprecipitated with RIOK2 and mTOR in U251 glioma cells." (PMID 33628587, 2021). "Both BYSL and RIOK2 positively regulated AKT/mTOR signaling, which might be responsible for the promoting effects of BYSL on human glioma growth." (PMID 33628587, 2021). "Finally, intracranial xenograft experiments confirmed the oncogenic roles of BYSL and RIOK2 in glioma growth." (PMID 33628587, 2021). "Immunohistochemistry showed that BYSL immunoreactivity was located in both the cytoplasm and nuclei and that the percentage of BYSL-IR cells was significantly increased in grade III (P < 0.001) and grade IV (P < 0.001) glioma tissues." (PMID 33628587, 2021). "Furthermore, we found a significantly positive correlation between BYSL and RIOK2 gene expressions in LGG (R = 0.49, P = 1.3e-32), GBM (R = 0.30, P = 7.8e-05), and various grades of glioma tissues (R = 0.253, P = 2.7e-05) by analyzing public datasets." (PMID 33628587, 2021). "Western blot analysis showed that BYSL protein levels were increased in grade II (n = 11, P = 0.068), grade III (n = 11, P < 0.001), and grade IV (n = 11, P = 0.001) glioma tissues compared to those in nontumor brain tissues (n = 9)." (PMID 33628587, 2021). "The BYSL mRNA levels showed a significant increase in grade II (n = 24, P = 0.043), grade III (n = 85, P < 0.001) and grade IV (n = 159, P < 0.001) in glioma tissues when compared to those in nontumor tissues." (PMID 33628587, 2021). "Western blot analysis of our cohorts also showed a significantly positive correlation between BYSL and RIOK2 expressions in glioma tissues (n = 33, R = 0.608, P < 0.001) but not in nontumor brain tissues (n = 9, R = 0.377, P = 0.317)." (PMID 33628587, 2021).
glioma (continued). "Using our cohorts, i.e., 25 glioma tissues (grade II, n = 9; grade III, n = 8; and grade IV, n = 8) and 8 nontumor brain tissues, qRT-PCR assays showed increased BYSL mRNA levels in grade II (P < 0.001), grade III (P = 0.028), and grade IV (P < 0.001) glioma tissues." (PMID 33628587, 2021).
hepatocellular carcinoma (5 papers, 2020 to 2023). A malignant tumor that arises from hepatocytes. "In vitro and in vivo experiments have shown that BYSL promotes hepatocellular carcinoma (HCC) cell survival and tumorigenesis." (PMID 33628587, 2021). "BYSL is upregulated in hepatocellular carcinoma, and as a crucial oncogene contributes to tumor cell growth both in vitro and in vivo." (PMID 32087603, 2020). "Meanwhile, knockdown of BYSL decreases the proliferation of hepatocellular carcinoma cells." (PMID 37186134, 2023). "BYSL may be an oncogene in various cancer, including hepatocellular carcinoma, glioblastoma, and diffuse large B-cell lymphoma." (PMID 34168991, 2021).
glioblastoma (4 papers, 2020 to 2022). The most malignant astrocytic tumor (WHO grade IV). "Furthermore, high expression of BYSL in glioblastoma has been shown to strongly correlate with markers of mesenchymal glioblastoma." (PMID 35154253, 2021). "Furthermore, BYSL enhances glioblastoma cell migration, invasion, and EMT by controlling the GSK-3β/β-catenin pathway." (PMID 35154253, 2021). "However, the role and mechanism of BYSL in glioblastoma (GBM) cell migration and invasion remain unknown." (PMID 33178594, 2020).
breast carcinoma (3 papers, 2008 to 2023). "Significant associations between increased tumour expression levels of BYSL and C6orf49 transcripts and breast cancer survival emerged." (PMID 18507837, 2008). "Although the results for BYSL are unclear, both analyses showed consistent associations of elevated tumour expression of the C6orf49 transcript with survival after a diagnosis of breast cancer." (PMID 18507837, 2008). "Previous investigation reveals that BYSL is enhanced in breast cancer, intestinal adenocarcinomas or gastric cancer, and may promote cell proliferation by facilitating 18S rRNA processing." (PMID 37186134, 2023).
liver cancer (2 papers, 2020). An epithelial or non-epithelial malignant neoplasm that arises from the liver. "BYSL is highly expressed in liver cancer, in ovarian cancer tissues, and in prostate cancer cells near the peripheral nerves." (PMID 33178594, 2020). "For instance, BYSL, which is required for ribosome processing, is pan‐dependent, and the expression is predicted to be unfavorable in liver cancer and renal cancer." (PMID 32744794, 2020). "BYSL is upregulated in reactive astrocytes in response to brain injury or inflammation and promotes liver cancer cell survival and tumorigenesis." (PMID 33178594, 2020). "Similarly to BYSL, it is pan‐dependent and the expression is unfavorable in both liver cancer and renal cancer." (PMID 32744794, 2020).
lung carcinoma (2 papers, 2021). "Interestingly, we found that two highly connected novel genes BYSL and BOP1 were significantly overexpressed in TCGA lung cancer tumor samples and their expression levels were obviously correlated with the survival of lung cancer patients." (PMID 34131148, 2021).
cardiac arrest (1 paper, 2018). Cessation of breathing and/or cardiac function. "BYSL expression in the cytoplasm of cortical neurons was minimal in the control group (cardiac arrest)." (PMID 29349722, 2018). "Minimal BYSL expression in control group shows, that ischemic brain injury in cardiac arrest may also be distinguished and recognized with this technique." (PMID 29349722, 2018).
osteosarcoma (1 paper, 2021). A usually aggressive malignant bone-forming mesenchymal neoplasm, predominantly affecting adolescents and young adults. "Moreover, multivariate Cox regression analysis indicated that BYSL and metastasis are independent risk factors for the total survival rate of patients with osteosarcoma." (PMID 35154253, 2021). "In summary, the present study demonstrates that BYSL is an independent factor for evaluating the prognosis of patients with osteosarcoma." (PMID 35154253, 2021). "In this study, we used the GSE126209 dataset from the GEO database to evaluate BYSL level using the limma package in R. Osteosarcoma tissues were found to have higher BYSL expression than adjacent paratumor tissues." (PMID 35154253, 2021). "Together, these results indicate that BYSL regulates the EMT of osteosarcoma cells via Nrf2 signaling under hypoxic conditions." (PMID 35154253, 2021). "In the present study, the roles of BYSL and miR-378a-3p in osteosarcoma cell lines were examined, and their functional relationship was assessed." (PMID 35154253, 2021). "To further identify the role of BYSL in osteosarcoma, we first examined its expression in tissue samples of 51 patients with osteosarcoma through histopathological analysis." (PMID 35154253, 2021). "Associations between clinicopathological characteristics and BYSL expression in patients with osteosarcoma." (PMID 35154253, 2021). "Taken together, these data suggest that BYSL has considerable clinical significance in the prognosis and metastasis of patients with osteosarcoma." (PMID 35154253, 2021). "It was also found that hypoxia increased the nuclear and total expression of BYSL in osteosarcoma cells." (PMID 35154253, 2021). "Next, the association between clinicopathological characteristics of the osteosarcoma patients and tissue BYSL expression was analyzed." (PMID 35154253, 2021). "Under normoxic conditions, miR-378a-3p knockdown greatly promoted the invasive and migratory potential of human osteosarcoma cells, and knockdown of BYSL rescued the miR-378a-3p-induced effects on osteosarcoma cells." (PMID 35154253, 2021). "Herein, the protein expression and clinical role of BYSL in human osteosarcoma tissues were assessed." (PMID 35154253, 2021). "Next, western blot was conducted to investigate the pathway of how BYSL modulates EMT in osteosarcoma cells." (PMID 35154253, 2021). "BYSL overexpression decreased epithelial marker (E-cadherin) and increased mesenchymal marker (N-cadherin and Vimentin) of osteosarcoma cells in hypoxia." (PMID 35154253, 2021). "Western blot and apoptosis analyses demonstrated that miR-378a-3p overexpression increased apoptosis in osteosarcoma cells under hypoxic conditions, which was inhibited by BYSL overexpression." (PMID 35154253, 2021). "In 51 cases of osteosarcoma tissues, BYSL was highly expressed in 20 cases and lowly expressed in 31 cases." (PMID 35154253, 2021). "Together, these findings suggest that BYSL is a pro-oncogenic protein and, thus, BYSL inhibition may represent a promising molecular therapeutic strategy for treating osteosarcoma in humans." (PMID 35154253, 2021). "Interestingly, miR-378a-3p overexpression rescued the effects of hypoxia on osteosarcoma cells, indicating that miR-378a-3p decreased hypoxia-induced BYSL expression to inhibit EMT." (PMID 35154253, 2021). "Osteosarcoma cells transfected with miR-378a-3p mimic had decreased BYSL and Nrf2 expression." (PMID 35154253, 2021). "Mechanistically, upregulation of BYSL enhanced Nrf2 expression under hypoxia in osteosarcoma cells." (PMID 35154253, 2021). "However, the clinical role and molecular mechanism of BYSL in osteosarcoma metastasis remain unclear." (PMID 35154253, 2021). "However, the function of BYSL in osteosarcoma remains poorly understood." (PMID 35154253, 2021).
osteosarcoma (continued). "In the present study, BYSL overexpression promoted EMT in MG63 and Saos-2 cells, indicating that BYSL may exert a critical effect on the invasive and aggressive behavior of osteosarcoma." (PMID 35154253, 2021).
ovarian carcinoma (1 paper, 2020). A malignant neoplasm originating from the surface ovarian epithelium. "It has been reported that BYSL has an oncogenic role in breast, prostate, liver, and ovarian cancer." (PMID 33178594, 2020).
prostate carcinoma (1 paper, 2020). A carcinoma that arises from epithelial cells of the prostate gland. "Previous studies have revealed that BYSL has important roles in embryo implantation and prostate cancer infiltration." (PMID 33178594, 2020). "In addition, BYSL promotes the growth and invasion of prostate cancer cells." (PMID 33178594, 2020). "Importantly, BYSL is highly expressed in neural infiltration models of prostate cancer." (PMID 33178594, 2020).
retinal tumors (1 paper, 2014). "While atf3 was dramatically increased in expression in the Tg(flk1:RFP)is18 retinal tumors, zebrafish bystin-like (bysl) showed no change in expression level." (PMID 25485542, 2014).
teratocarcinoma (1 paper, 2016). A germ cell tumor characterized by the presence of an embryonal carcinoma component and a teratoma component. "BYSL, together with keratin 18 are thought to be involved in teratocarcinoma." (PMID 27955658, 2016).